APC (APC regulator of Wnt signaling pathway)
Diseases named in the same sentence as APC in open-access papers (continued):
Sharing a sentence is not in itself a finding about the gene and the disease.
adenoma (continued). "In particular, loss of APC and consequent increase in β-catenin facilitates the formation of adenoma, thereby initiating the adenoma-carcinoma sequence for colorectal tumorigenesis." (PMID 28035994, 2016). "In conclusion, we identified two CRC-associated SNPs, rs16892766 (8q23.3) and rs3802842 (11q23.1), which show an association with adenoma number in APC mutation carriers." (PMID 26880076, 2016). "Mice with mutated adenomatous polyposis coli (APC), a negative regulator of Wnt signalling and frequent mutation target, rapidly develop adenoma in the small intestine and colon." (PMID 27534699, 2016). "An attenuated FAP phenotype results in generally fewer than 100 adenomas, and fewer than 10% of such families have detectable APC mutations." (PMID 25941542, 2015). "The classical FAP phenotype results in the growth of hundreds to thousands of adenomas, caused in approximately 70% to 80% of affected families by germline mutations in the tumor suppressor gene adenomatous polyposis coli (APC) on chromosome 5q21-22." (PMID 25941542, 2015). "At the same time, HNPCC tumours show some of the characteristics of conventional adenomas, such as the presence of mutations of APC, β-catenin (CTNNB1), and/or K-ras." (PMID 25932044, 2015). "In APC-deficient adenoma, accumulation of β-catenin complexed with nuclear TCF4 results in the increased expression of its oncogenic target genes, such as cyclin-D1 that promotes intestinal cell proliferation and polyp formation." (PMID 26500891, 2015). "This pathway is activated at the very early stage of colon carcinogenesis, namely 50–70% of early and medium adenomas carry the mutation in the APC gene." (PMID 25526641, 2014). "An attenuated form of FAP (AFAP), characterized by less than 100 adenomas, occurs with APC germline mutations involving the 5′ or 3′ region of the gene." (PMID 23965959, 2013). "For DKK3, 95% (38/40) of the APC mutated samples showed DKK3 methylation whereas only 78% (32/41) showed DKK3 methylation in the APC wild type adenomas (p = 0.026)." (PMID 24350795, 2013). "Of the APC mutated adenomas 83% (33/40) showed WIF-1 methylation and of the APC wild type adenomas 61% (25/41) showed WIF-1 methylation (p = 0.048)." (PMID 24350795, 2013). "Of note, all of the adenomas analyzed exhibited APC inactivating mutations (exon 15) in combination with KRAS (G12D, G13D, Q61H) or BRAF (V600E) activating mutations." (PMID 23919615, 2013). "First, APC was mutated in both adenoma and adenocarcinoma; thus this study confirmed that the Wnt pathway was activated in the early stage of colorectal tumor development." (PMID 23301059, 2013). "The E1353X mutation of APC was detected in one additional case of adenoma, and was also reported in colorectal adenocarcinomas." (PMID 23301059, 2013). "Combining both adenoma types, a positive trend between APC mutation and both WIF-1 and DKK3 methylation was observed (p < 0.05)." (PMID 24350795, 2013). "In adenomas that develop due to APC mutations, tissue disorganization is manifest as dysplasia, and premalignant tumor growth results from an increased rate of intestinal crypt fission." (PMID 24224156, 2013). "Although, flat adenomas showed a lower frequency of APC mutations compared to polypoid adenomas, they were previously found to have higher frequency of chromosome 5q loss, including the APC gene locus." (PMID 22848674, 2012). "Types IIa, LST-G and LST-F flat adenomas all contained significantly fewer APC mutations compared to polypoid adenomas (IIa: 29.6% (8/27), LST-G: 25% (3/12), LST-F: 34.4% (11/32) vs polypoid 55.6% (45/81) p = 0.02, 0.05 and 0.04, respectively)." (PMID 22848674, 2012).
adenoma (continued). "APC mutations were more frequent in polypoid adenomas compared to flat adenomas (48.5% versus 30.3%, respectively, p = 0.02)." (PMID 22848674, 2012). "According to the COSMIC database, the MCR harbors 76.37% of all the mutations described in the APC gene for adenomas." (PMID 22848674, 2012). "From this study it appears that APC mutations and thus possibly the Wnt-signaling in general, would play a less prominent role in flat adenomas than in polypoid adenomas." (PMID 22848674, 2012). "We previously found significantly more chromosome 5q loss (APC locus) in flat adenomas compared to polypoid adenomas." (PMID 22848674, 2012). "It has been established that mutations in theadenomatous polyposis coli (APC) gene arelikely to be critical events in the initiation of the majority of adenomas and CRC." (PMID 21408169, 2011). "Out of 5 affected members' tissues, the adenomas from Number 3 were exclusively found somatic loss of wild-type APC allele." (PMID 22164339, 2011). "The basic version of our CRC model assumes that adenoma initiation occurs when the remaining wild-type copy of the APC tumor suppressor gene is deleted or mutated in a stem cell of a (pre-initiated) APC+/− colonic crypt." (PMID 22022253, 2011). "A limited number of lesions in this study carried more than one mutated gene, the most frequent mutation “combinations” being APC/K-Ras (in three adenomas) and APC/B-Raf (in one serrated lesion and three adenomas)." (PMID 24212608, 2010). "Whereas β-catenin is constitutively activated through mutation of the tumor suppressor APC in the majority of adenomas the relative overexpression of γ2 at the invasive edge of carcinomas requires additional alterations." (PMID 20307265, 2010). "Whereas alterations in the APC mutation cluster region were only observed in ten percent of the serrated lesions, 34.1% of the adenomas exhibited mutations." (PMID 24212608, 2010). "In the case of APC, a higher mutation frequency was observed in adenomas arising in the distal colon when compared to those in the proximal colon." (PMID 24212608, 2010). "We use the human adenoma cell line LT97 carrying mutations of the APC and Ki-ras genes as a model for early stage premalignant tumor cells with intact Smad4." (PMID 20307265, 2010). "The mouse model of FAP contains a point mutation in the APC gene; it develops numerous adenomas and was the first model used to study the involvement of the APC gene in intestinal tumorigenesis." (PMID 19822006, 2009). "The indication for genetic testing include: clinical criteria that meet AFAP or having a first-degree relative with a known APC mutation or multiple adenomas." (PMID 19822006, 2009). "Mouse knockout models of APC/DCC have shown that loss of the DCC gene in mice that have adenomas initiated by APC loss causes a bias towards highly dysplastic adenomas." (PMID 19424478, 2008). "APC mutations have been observed in 30-70% of sporadic adenomas and in 34-72% of sporadic carcinomas." (PMID 19424478, 2008). "Adenomas as small as 0.5cm carry APC mutations, reinforcing the theory that these are initiators of a cascade of genetic changes leading to carcinogenesis." (PMID 19424478, 2008). "When dividing adenoma cases based on APC truncation mutation status a statistically significant association was detected for "ever smoked" and APC- adenomas only." (PMID 16545110, 2006). "For example, the adenoma-carcinoma sequence is characterized by nearly ubiquitous aberrations in the wnt signaling pathway, such as APC or β-catenin gene mutations." (PMID 17166268, 2006).
adenoma (continued). "We detected fewer APC silent/missens mutations than a resent Dutch study did, but the frequencies of truncated mutations detected for CRC and adenomas are comparable to published studies on APC truncation mutations (30–45%)." (PMID 16545110, 2006). "APC truncation mutations were detected in 40% of the adenomas (18/43) and in 32% of the CRC tumors (27/84), respectively." (PMID 16545110, 2006). "Distribution of selected smoking characteristics for adenoma and carcinoma cases divided by APC truncation-mutation status." (PMID 16545110, 2006). "APC mutational spectra detected in all adenoma/CRC cases, and cases divided according to smoking status." (PMID 16545110, 2006). "Early development of a large number of colon adenomas in this disorder indicates that mutations in the APC gene can be rate-limiting in adenoma development." (PMID 15982419, 2005). "The majority of IEC-18 cells in SFM alone had a loss in expression of the adenomatous polyposis coli (APC) gene at the mRNA and protein levels, consistent with adenoma-like transformation." (PMID 15656904, 2005). "Transcripts of PSG9 were detected in 78% (14/18) of adenomas from FAP cases with APC germline mutations." (PMID 15982419, 2005). "APC mutation: the frequency in superficial depressed adenomas was lower than that in polypoid adenomas (7% vs 43%: P = 0.016), and that in polypoid carcinomas was similar to that in non-polypoid carcinomas." (PMID 10638959, 2000). "It is possible that new APC mutations are acquired after the development of superficial depressed adenomas." (PMID 10638959, 2000). "According to a meta-analysis study by Liang and colleagues, there was a significant relationship between the risk of CRC incidence and the frequency of APC promoter hypermethylation, and this frequency was significantly higher in adenoma tissues compared to normal colorectal tissues." (PMID 40521787, 2025). "The APC mutation was found in 94/114 (82.5%) cases of sporadic adenomas." (PMID 39977302, 2025). "Accumulating genetic evidence supports a multistep model of tumor progression, in which early APC loss leads to chromosomal instability and adenoma formation, followed by activating mutations in KRAS that synergize with β-catenin signaling to promote tumor growth and invasion." (PMID 41294868, 2025). "Similarly, we observed a high frequency of intranuclear expression of β-catenin and APC mutations in intestinal-type adenomas." (PMID 40463821, 2025). "Interestingly, these mice presented a small intestinal phenotype, whereas humans with APC mutations develop adenomas in the colon." (PMID 40624028, 2025). "In APC-deficient adenomas, the deletion of JAG1 disrupts stem cell niche formation." (PMID 41294868, 2025). "Specifically, loss of APC canonical function induces alterations in intestinal differentiation, and the transcriptional corepressor C-terminal binding protein-1 (CtBP1) influences the adenoma initiation." (PMID 40075600, 2025). "Additionally, we observed a high frequency of GNAS mutations in gastric-type adenomas and APC mutations in intestinal-type adenomas, with a tendency towards mutual exclusivity." (PMID 40463821, 2025). "Our findings pose the following question: if the adenoma-carcinoma pathway that is initiated by APC mutation is blocked by colonoscopy and the carcinogenetic pathway has to include an early mutation causing an increased cell proliferation rate, how have the observed CRCs emerged?" (PMID 38741120, 2024).
adenoma (continued). "Both adenomas in patient P2 harbored the same APC (Q1285X) and KRAS (G12S) mutations." (PMID 39554798, 2024). "Furthermore, these individuals acquire biallelic APC mutations, with loss of function in one allele followed by an acquired mutation in the second allele of APC in the adenomas and adenocarcinomas that develop." (PMID 38590663, 2024). "Interestingly, a specific somatic mutation, APC p.R1450*, was found in certain adenomas of all three patients." (PMID 39021676, 2024). "However, the interpretation of PV detected in APC in adenomas or carcinomas can prove challenging as somatic variants in APC are common in these tumors and because many APC variants have been reported, both somatically and germline." (PMID 38467732, 2024). "Notably, APC mutation was observed in all cases, which confirmed Wnt activation was the major driving factor of primary adenoma." (PMID 37667332, 2023). "Also in a recent study, whole exome sequencing in 9 MSH3-related adenomas showed pathogenic somatic APC variants in all but one adenoma." (PMID 35675019, 2023). "This study suggests that a single truncating mutation of the APC gene may initiate adenoma formation." (PMID 36826061, 2023). "Another study using ApcMin/+ mice highlighted how APC gene mutation could disrupt the interactions between the colonic mucosa and the microbiota, even prior to adenoma development, through the modification of the relative abundance of bacterial species." (PMID 36982759, 2023). "FAP accounts for 1% of all CRCs and its distribution is the same for men and women; it is characterized by hundreds to thousands of adenoma developing in the colon and the rectum due to the germline mutation in adenomatous polyposis coli (APC) gene and shows the classic adenoma–carcinoma sequence." (PMID 38202047, 2023). "In stark contrast to the tubular adenomas in the adenoma–carcinoma pathway, in which APC inactivation is a founder mutation for Wnt activation leading to the formation of the early tubular adenoma lesions, sessile serrated adenomas tend to significantly lack APC mutations." (PMID 35975243, 2022). "This is notable since LS colorectal tumorigenesis is generally thought to follow the classic adenoma-carcinoma sequence, whereby MMRd is a late event in adenomas, with established Wnt signaling activation due to somatic APC, CTNNB1 or RNF43 PVs, that causes rapid progression to carcinoma." (PMID 36291559, 2022). "The location of the constitutional APC pathogenic variant can predict the colorectal phenotype with a pathogenic variant in the mutation cluster region (codon 1,250 to 1,450) predicting higher adenoma number compared with those at the 3′ or 5′ of the APC gene." (PMID 35297393, 2022). "This body of evidence suggests that APC mutations that transform normal mucosa to adenomas to colon cancer may also play a role in increasing the risk of PDAC through mutations in IPMNs." (PMID 35884779, 2022). "Effective targeted therapies are now available for some of the affected signaling pathways, such as the NSAIDs sulindac and celecoxib that significantly reduce adenoma load in patients with APC germline mutations, probably because of the typical inhibition of the WNT/β-catenin signaling pathway." (PMID 36551963, 2022). "Thus, these CRCs were considered to develop through a conventional pathway (i.e. the adenoma–carcinoma sequence initiated by APC two‐hit mutations)." (PMID 35040131, 2022).
adenoma (continued). "Therefore, mutations in components of the Wnt pathway have very early roles in the serrated pathway, similar to the role of APC mutations in driving the adenoma–carcinoma pathway in CRC." (PMID 35975243, 2022). "Similarly, PAR1 deficiency on the adenomatous polyposis coli mutant (APC Min) background resulted in more and larger adenomas suggesting that PAR1 limits premalignant transformation in prostate and intestinal tumors." (PMID 33932087, 2021). "The genetic profile of colonic lesions showed that RNF43 gene mutations were frequent in both LS-associated adenomas and adenocarcinomas, while APC gene mutations, despite being detected in 40% of LS-adenomas, were more frequent in sporadic colorectal adenomas (60% of cases)." (PMID 33923068, 2021). "Indeed, the YAP-mediated regenerative response can be hijacked to facilitate the progression of APC-deficient foci to adenomas to the extent that Yap deletion abrogates adenoma formation in ApcMin/+ mice." (PMID 33673710, 2021). "Consequently, ISCs proliferate rapidly and increase adenoma formation in a mouse model of APC loss-induced intestinal tumorigenesis." (PMID 34887764, 2021). "Furthermore, it shows that a single heterozygous APC mutation can alter the molecular and cellular phenotype of cells and provide a selective advantage of adenoma formation during CRC development." (PMID 33664379, 2021). "Conversely, APC-deficient Lgr5+ ISCs drive rapid adenoma formation in the mouse small intestine." (PMID 33673710, 2021). "CCR4-NOT Transcription Complex Subunit 3 (CNOT3), a gene important for regulating mRNA transcription, was identified as the most commonly mutated gene (excluding APC) in 20% of 37 FAP adenomas compared to only 1% in the sporadic/inherited colon cancer subset from the TGCA dataset." (PMID 33987182, 2021). "In our study, we found APC somatic mutations in adenomas of CHEK2 mutant carriers." (PMID 34549727, 2021). "When the ISC compartment harbors APC mutations, it undergoes an uncontrolled expansion followed by adenoma formation, as also confirmed in the mouse genetic models where adenomas appeared only in case of APC mutations targeting to ISCs rather than differentiated cells." (PMID 33673612, 2021). "In addition, the number of variants in the APC MCR was similar to that observed in sporadic adenomas which points to the oncogenic relevance of the MCR for tumourigenesis irrespective of the underlying mutation type." (PMID 34843512, 2021). "Loss of heterozygosity (LOH) at 5q21, where the APC gene is located, has been demonstrated in 70% of sporadic ampullary tumors, comprehensive of 75% of adenomas and early-stage cancers, and this also suggests its contribution in the early phase of carcinomas development." (PMID 33922305, 2021). "Serrated adenomas of the intestine that are associated with a BRAF mutation show molecular, morphological, clinical, and epidemiological characteristics that differ from those of adenomas and which develop during a “classic adenoma-carcinoma sequence” based on mutations of the APC gene." (PMID 34259881, 2021). "An alternative hypothesis, supporting an age at diagnosis that is similar to conventional pathway cancers and the morphology of our murine adenomas, is that polyps are initiated by APC, acquiring a BRAF mutation." (PMID 32384699, 2020).